HBP1 (HMG-box transcription factor 1)
Diseases named in the same sentence as HBP1 in open-access papers (continued):
Sharing a sentence is not in itself a finding about the gene and the disease.
hepatocellular carcinoma (5 papers, 2016 to 2022). A malignant tumor that arises from hepatocytes. "Compared to wild-type mice, HBP1-deficient mice developed more severe liver damage, liver fibrosis, and ultimately induced hepatoma with higher malignancy." (PMID 33794968, 2021). "The deregulation of AFP by HBP1 is associated with hepatoma cell metastasis and poor survival of hepatoma patients." (PMID 33794968, 2021). "Hepatitis B Virus (HBV)-encoded protein HBx promoted malignancy in hepatoma cells through binding to HBP1 directly." (PMID 33794968, 2021). "We constructed HBP1-deficient mice to investigate the role of HBP1 in the development of hepatoma." (PMID 33794968, 2021). "In addition, HBx, a HBV regulatory protein that promotes the development of HBV-associated hepatoma, can interact with HBP1, inhibiting the binding of HBP1 to the AFP promoter region and leading to up-regulated AFP expression." (PMID 33794968, 2021). "In addition, we constructed HBP1-deficient mice and induced hepatoma model by DEN/CCl4." (PMID 33794968, 2021). "HBP1 may be an inhibitor in the development of HBV-associated hepatoma." (PMID 33794968, 2021). "In this study, we found a transcriptional regulatory mechanism to regulate the progression of hepatoma between HBP1 and AFP." (PMID 33794968, 2021). "In the present study, we found that HBP1 expression was also downregulated in hepatoma tissues, and overexpression of HBP1 in hepatoma cells transcriptionally inhibited AFP expression and decreased cell proliferation and migration." (PMID 33794968, 2021). "Icaritin, an active ingredient of Chinese herb epimedium, inhibited malignancy in hepatoma cells through enhancing HBP1 transrepression of AFP." (PMID 33794968, 2021). "IHC staining of paraffin sections showed that Ki67 expression was higher in HBP1-deficient mice compared with wild-type mice, indicating that HBP1-deficient mouse hepatoma was more malignant in the DEN/CCl4-induced hepatoma model." (PMID 33794968, 2021). "The identification of a mechanism by which high HBP1 expression inhibits hepatoma progression opens up new therapeutic avenues for hepatoma therapy." (PMID 33794968, 2021). "Together, HBx or Icaritin mediates proliferation and migration of hepatoma cells through regulating the HBP1-AFP axis." (PMID 33794968, 2021). "To further investigate the function of HBP1 in the development of hepatoma, we constructed HBP1 knockout mice using the CRISPR/Cas9 system." (PMID 33794968, 2021). "We also found that high expression of HBP1 correlated with increased survival and prognosis in the hepatoma patient group examined in this study." (PMID 33794968, 2021). "Therefore, we exogenously overexpressed HBP1 in human hepatocellular carcinoma-derived HepG2 cells, PLC hepatoma cells, and normal liver L02 cells, and this increased both the protein and mRNA expression of IGFBP1 in all three cell lines." (PMID 36326689, 2022). "The repression of AFP by HBP1 inhibited the malignancy of hepatoma cells." (PMID 33794968, 2021). "The deregulation of AFP by HBP1 contributed to hepatoma progression in mice." (PMID 33794968, 2021). "We suggest that HBP1 expression level may be a useful indicator in the treatment and prognosis monitoring of hepatoma to better improve the prognosis of patients with hepatoma." (PMID 33794968, 2021).
hepatocellular carcinoma (continued). "We observed a significant inverse correlation between HBP1 and AFP protein levels in hepatoma tissues by immunohistochemical staining." (PMID 33794968, 2021). "The repression of AFP by HBP1 attenuates AFP effect on PTEN, MMP9 and caspase-3, thus inhibits proliferation and migration, and induces apoptosis response to oxidative stress in hepatoma cells." (PMID 33794968, 2021). "Our data clarify the mechanism of HBP1 in inhibiting the expression of AFP and its suppression in malignancy of hepatoma cells, providing a more comprehensive theoretical basis and potential solutions for the diagnosis and treatment of hepatoma." (PMID 33794968, 2021). "The expression of transcription factor HBP1 and AFP and clinical significance were further analyzed in hepatoma tissues from the patients who received surgery or TACE and then monitored for relapse for up 10 years." (PMID 33794968, 2021). "Together, the data suggest that HBP1 deletion aggravates DEN/CCl4-induced liver damage, hepatic fibrosis and hepatoma in mice." (PMID 33794968, 2021). "The relative expressions of HBP1 and AFP correlated with survival and prognosis in hepatoma patients." (PMID 33794968, 2021). "Here, we show that HBP1 regulates AFP expression at the transcriptional level and inhibits the development of hepatoma." (PMID 33794968, 2021). "The data suggest that the inverse expressions of HBP1 and AFP correlate with relapse and survival in hepatoma patients." (PMID 33794968, 2021). "Since HBP1 and AFP play a key role in the development of hepatoma, studies on the regulation of HBP1 and AFP are crucial in maintaining the normal physiological function of the liver and the diagnosis and treatment of liver cirrhosis and hepatoma." (PMID 33794968, 2021). "HBP1 low expression and/or AFP high expression in hepatoma can be correlated with low survival rate." (PMID 33794968, 2021). "During hepatoma progression, this biological process could be reversed by aberrantly low HBP1 expression, which promotes AFP effect on PTEN, MMP9 and caspase-3, thus induces proliferation and migration, and inhibits apoptosis in hepatoma cells." (PMID 33794968, 2021). "The inverse relationship of HBP1 and AFP in hepatoma patients correlates with hepatoma relapse." (PMID 33794968, 2021). "In addition, HBP1 protein level in HBV positive (HBs Ag+) hepatoma patients was lower than that in HBV negative (HBs Ag−) hepatoma patients." (PMID 33794968, 2021). "To determine whether HBx promotes the development of hepatoma through inhibiting the downregulation of AFP by HBP1, we overexpressed HBP1 with or without HBx in HepG2 cells." (PMID 33794968, 2021).
liver cancer (5 papers, 2016 to 2023). An epithelial or non-epithelial malignant neoplasm that arises from the liver. "Since AFP is a serum marker of primary liver cancer, we evaluated the AFP content in mouse serum using ELISA and found that serum AFP level of HBP1-deficient mice was higher than that of wild-type mice." (PMID 33794968, 2021).
osteosarcoma (5 papers, 2016 to 2020). A usually aggressive malignant bone-forming mesenchymal neoplasm, predominantly affecting adolescents and young adults. "MiR-155 is also overexpressed in osteosarcoma samples in comparison to corresponding normal tissue and targets the Wnt pathway repressor HMG-box transcription factor 1 (HBP1), thereby driving osteosarcoma cell proliferation by enhancing Wnt pathway action." (PMID 32806571, 2020).
prostate carcinoma (5 papers, 2012 to 2018). A carcinoma that arises from epithelial cells of the prostate gland. "According to these results, it can be envisaged that increased expression of HBP1 can enhance the radiosensitivity of prostate cancer cells, whereas reduced expression level of HBP1 in prostate cancer cells is likely to be an important cause of prostate cancer radioresistance." (PMID 26942107, 2016). "In prostate cancer, HBP1 directly targeted the MIF promoter and inhibited its transcription, which remarkably blocked cell growth and invasion." (PMID 29367693, 2018). "Through research on prostate cancer cells in vitro, we found that HBP1 expression levels were negatively correlated with oncogene expression levels." (PMID 26942107, 2016). "Our preliminary results showed that DU-145 prostate cancer cell lines with high expression level of HBP1 were more sensitive to radiation." (PMID 26942107, 2016). "Presently, while much is known about the upstream regulation of HBP1, little is known about its downstream targets and their roles in radiotherapy in the treatment of prostate cancer." (PMID 26942107, 2016). "In this study, the clinical data of patients with prostate cancer was compared, and the positive correlation was revealed between prostate cancer brachytherapy efficacy and the expression level of HBP1 gene." (PMID 26942107, 2016). "Our recently published study showed that the expression level of HBP1 in prostate cancer cells and prostate cancer tissues was significantly lower than the normal cells and normal adjacent matched tissues, respectively." (PMID 26942107, 2016). "Taken together, our data demonstrated that suppression of HBP1 expression not only sensitized prostate cancer cells to radiation but also increased apoptosis in prostate cancer cells." (PMID 26942107, 2016). "In this study, we combined clinical data of patients with prostate cancer, prostate cancer cells, and animal models to analyze the relationship between HBP1 gene and prostate cancer radiosensitivity." (PMID 26942107, 2016). "HBP1 was reported to be a tumor repressor in several cancers including prostate cancer, non-small cell lung carcinoma (NSCLC) and breast cancer, in which it also induced cell cycle arrest and promoted cell apoptosis by inhibiting Wnt/β-catenin pathway signal transduction." (PMID 29367693, 2018). "The results suggest that upregulation of HBP1 expression could enhance the short-term apoptotic effects of radiation or reduce radiation-resistant prostate cancer." (PMID 26942107, 2016). "New technologies, such as gene chips, could be employed to determine the downstream effectors of HBP1 in prostate cancer radiotherapy." (PMID 26942107, 2016). "Other reports suggest a similar role for a decrease in HBP1 in prostate cancer." (PMID 27129219, 2016). "Furthermore, we determined the relationship between HBP1 and apoptosis during prostate cancer radiotherapy." (PMID 26942107, 2016). "Though the expression level of HBP1 in prostate cancer is closely related to metastasis and prognosis, the relationship between HBP1 and prostate cancer radiotherapy is unknown." (PMID 26942107, 2016). "In our previous study, we showed that the expression level of HBP1 was closely related to prostate cancer metastasis and prognosis, but the relationship between HBP1 and radioresistance for prostate cancer is largely unknown." (PMID 26942107, 2016). "Similarly, HBP1 knockdown hastens cell migration and invasion in breast and prostate cancer cells." (PMID 28099936, 2017). "Thus, HBP1, which regulates cell cycle progression, likely modulates radiation-induced apoptosis in prostate cancer cells, therefore affecting the efficiency of radiotherapy in prostate cancer cells." (PMID 26942107, 2016). "Therefore, we hypothesized that decreased expression of HBP1 in prostate cancer leads to radioresistance." (PMID 26942107, 2016).
prostate carcinoma (continued). "In addition, animal model was employed to analyze the relationship between HBP1 gene and prostate cancer radiosensitivity in vivo; the result showed that knockdown of HBP1 gene could decrease the sensitivity to radiation of xenograft." (PMID 26942107, 2016). "Furthermore, HBP1 overexpression could sensitize prostate cancer cells to radiation and increase apoptosis in prostate cancer cells." (PMID 26942107, 2016). "Lower expression level of HBP1 resulted in the increased expression level of MIF gene (macrophage migration inhibitory factor) and promoted the ability of colony formation and invasion of prostate cancer cells." (PMID 26942107, 2016).
lung adenocarcinoma (4 papers, 2015 to 2022). A carcinoma that arises from the lung and is characterized by the presence of malignant glandular epithelial cells. "Our study herein was conducted to evaluate the biological roles of miR‐21/HBP1 in lung adenocarcinoma growth, migration, and invasion, and to identify HBP1 as a target of miR‐21." (PMID 29663730, 2018). "Similar to HBP1, p21 was down-regulated in colorectal adenocarcinoma, lung adenocarcinoma, and lung squamous cell carcinoma, and so forth." (PMID 27129219, 2016). "Overall, our findings indicate that miR‐21 functions as a tumor facilitator in lung adenocarcinoma through targeting HBP1 and may be a promising candidate for miR‐based therapy against lung adenocarcinoma." (PMID 29663730, 2018). "In addition, we found that HBP1 and p21 were significantly down-regulated in lung adenocarcinoma, whereas EZH2 was significantly up-regulated in the cancer, according to bioinformatics analysis." (PMID 27129219, 2016). "Nevertheless, no study has thoroughly elaborated the role of HBP1 during lung adenocarcinoma development." (PMID 29663730, 2018).
breast tumors (3 papers, 2016 to 2021). "Concomitant reduction of mRNA expression levels of FOXO1 with HBP1 were also observed in a set of breast tumors." (PMID 28099936, 2017). "HBP1 is a tumor suppressor whose expression is lower in breast tumors targeted by the PIα/FOXO pathway." (PMID 27445062, 2016). "Additionally, HBP1 was found down-regulated in breast tumors compared to normal tissue from patients, which was associated with poor prognosis, RFS and relapse." (PMID 34681793, 2021).
cervical cancer (3 papers, 2019 to 2022). A primary or metastatic malignant neoplasm involving the cervix. "Taken together, our results demonstrate that elevated expression of methylated HBP1 and reduced levels of GSN in cervical cancer are associated with poorer prognosis." (PMID 35941115, 2022). "Our results indicated that FSCN1 is overexpressed in cervical cancer tissue and negatively regulates the expression of HBP1 in HeLa cells." (PMID 35178306, 2022). "To define whether HBP1 methylation can contribute to cancer progression, we used the HBP1 R378me1a antibody to detect the levels of methylated HBP1 in 70 cervical cancer tissue samples." (PMID 35941115, 2022). "Therefore, further study should be conducted to reveal the molecular mechanism by which FSCN1 regulates the expression of HBP1 and ANGPTL4 in cervical cancer." (PMID 35178306, 2022). "Thus, FSCN1 negatively regulates four transcription factors (HLTF, HBP1, ZNF664, DDX17) and positively regulates ANGPTL4 (an angiogenic factor) and EPHA2 in both HeLa cells and cervical cancer tissues." (PMID 35178306, 2022). "The results showed that the expression of FSCN1 had a significant negative correlation (P < 0.05) with that of HLTF, HBP1, ZNF664, CTGF, DDX17, and KRT18 in cervical cancer tissues." (PMID 35178306, 2022).
colitis (3 papers, 2021 to 2023). Inflammation of the colon. "miR-155 has been reported to promote colitis-associated intestinal fibrosis, targeting the HBP1/Wnt/β-catenin signaling pathway." (PMID 37761144, 2023). "Li et al24 showed that miR-155 promoted colitis-associated intestinal fibrosis through the pathway of Hd1 Binding Protein (HBP1)/Wnt/beta-catenin signaling." (PMID 37326155, 2023). "Consistent with the in vitro results, miR‐155 was demonstrated to suppress the protein expression of HBP1 in the TNBS‐induced colitis mouse model, as compared to the control group." (PMID 33769664, 2021).
colon carcinoma (3 papers, 2014 to 2017). "Similar observation was also reported by Coomans de Brachene and colleagues that the PI3K inhibitor LY294002 or other Akt inhibitor (Akt inhibitor VIII or MK 2206) caused increased mRNA or protein expression of HBP1 in either eosinophilic leukemia or colon carcinoma cells." (PMID 28099936, 2017). "In addition, the mechanism of HBP1 gene alteration in NSCLC remains unclear, although HBP1 mutation and gene deletion of HBP1 are reported in breast and colon cancers." (PMID 24895061, 2014).
Hepatic steatosis (3 papers, 2020 to 2023). Steatosis is a term used to denote lipid accumulation within hepatocytes.
invasive breast carcinoma (2 papers, 2014 to 2016). A carcinoma that infiltrates the breast parenchyma. "We had reported previously that HBP1 was decreased in invasive breast cancer and correlated with a poor prognosis." (PMID 27129219, 2016).
lymph node metastasis (2 papers, 2017 to 2018). "The mean mRNA level of either HBP1 or FOXO1 in non-invasive and invasive oral tumors (lymph node metastasis) was significantly lower than those of control normal tissues." (PMID 28099936, 2017).
nasopharyngeal carcinoma (2 papers, 2018 to 2024). A carcinoma arising from the nasopharyngeal epithelium. "However, our findings provide a conclusion that HBP1 plays a novel role in facilitating nasopharyngeal carcinoma (NPC) growth." (PMID 29367693, 2018).
squamous cell carcinoma (2 papers, 2014 to 2017). A carcinoma arising from squamous epithelial cells. "Low HBP1 protein expression correlated with squamous cell carcinoma patients (P = 0.046)." (PMID 24895061, 2014).
acute lymphoblastic leukemia (1 paper, 2024). Leukemia with an acute onset, characterized by the presence of lymphoblasts in the bone marrow and the peripheral blood. "In vitro and in vivo Acute Lymphoblastic Leukemia (ALL) models reveal that MIF is positively regulated by UHRF1 (ICBP90) and negatively regulated by HBP1, both of which drive MIF overexpression in disease progression by binding to the promotor region." (PMID 38732068, 2024).
cardiac hypertrophy (1 paper, 2024). "To study the function of HBP1 in the pathogenesis of cardiac hypertrophy, we generated HBP1‐overexpressing HL‐1 cell line using lentivirus vector." (PMID 38924383, 2024). "Overexpression of HBP1 significantly increased the levels of cardiac hypertrophy markers ANP, BNP, and β‐MHC." (PMID 38924383, 2024). "In conclusion, our findings suggest that overexpression of MIF regulates the miR‐29b‐3p/HBP1 axis and protects against pressure overload induced cardiac hypertrophy." (PMID 38924383, 2024). "In the current study, we used bioinformatics analysis to predict the potential target genes of miR‐29b‐3p and found out that HBP1 is a downstream target of miR‐29b‐3p which plays a vital role in cardiac hypertrophy." (PMID 38924383, 2024). "Taken together, MIF could attenuate pressure overload‐induced cardiac hypertrophy through regulating the miR‐29b‐3p/HBP1 axis." (PMID 38924383, 2024). "In conclusion, our findings suggest that MIF could attenuate pressure overload‐induced cardiac hypertrophy through regulating the miR‐29b‐3p/HBP1 axis." (PMID 38924383, 2024).
Cirrhosis (1 paper, 2021). A chronic disorder of the liver in which liver tissue becomes scarred and is partially replaced by regenerative nodules and fibrotic tissue resulting in loss of liver function. "Our results indicate that the presence of HBP1 protects the liver and delays the progression of hepatitis to cirrhosis, finally inhibiting tumorigenesis." (PMID 33794968, 2021). "Deletion of HBP1 is more likely to cause collagen (Type I and Type III) secretion and deposition, leading to the occurrence of cirrhosis in mice." (PMID 33794968, 2021).
colon adenocarcinoma (1 paper, 2016). "Intriguingly, a previous paper reported that HBP1 could repress the p21 promoter in Caco-2 cells, which were derived from colon adenocarcinoma." (PMID 27129219, 2016).